MYH9 (myosin heavy chain 9)
Diseases named in the same sentence as MYH9 in open-access papers (continued):
Sharing a sentence is not in itself a finding about the gene and the disease.
deafness (23 papers, 2009 to 2025). An inherited or acquired condition characterized by the complete loss of the ability to hear from one or both ears. "For example, pathogenic variants of Myh9 known to cause deafness in humans also cause morphological defects in scolopidia when overexpressed in Johnston's organ." (PMID 29853544, 2018). "We also describe recent work that indicates that some Usher syndrome proteins interact physically with Myosin II, the variants of which can cause MYH9-related diseases, including deafness." (PMID 29853544, 2018). "Many MYH9-related disorder patients exhibit sensorineural deafness, and variants of MYH9 have also been reported in non-syndromic deafness DFNA17." (PMID 27331610, 2016). "In the auditory epithelium, PCP pathways polarize NMII-driven contractile forces to pattern hair cells, which regulate sound perception, providing a possible mechanism for the deafness associated with MYH9-RD." (PMID 26542704, 2015). "Such disturbances may interfere with sound perception, potentially contributing to deafness, a condition linked with MYH9-related disorders." (PMID 39273383, 2024). "However, MYH9 mutations also lead to kidney defects, cataracts, and/or deafness, collectively known as MYH9 disease." (PMID 38042490, 2023). "However, the cellular basis of deafness in pathogenic variants of MYH9 is unclear as MYH9 is widely expressed within the inner ear." (PMID 27331610, 2016). "Another plausible candidate is MYH9, which has variants known to cause deafness in humans." (PMID 20967282, 2010). "However, distinguishing whether deafness in older individuals with MYH9-RDs is directly caused by gene mutation or is a separate age-related condition can be challenging." (PMID 38134071, 2023). "The severity of hearing impairment is variable among different patients: while in some MYH9-RD subjects the hearing defect is mild or moderate even at advanced age, in other patients hearing loss presents during childhood and progresses to profound deafness within the first decades of life." (PMID 24980457, 2014). "Thus, patients with a MYH9 mutation often suffer from nephritis, deafness and cataracts." (PMID 23976996, 2013). "Although deafness can occur in MYH9-RDs, further evaluation and genetic studies are needed to establish a clear association." (PMID 38134071, 2023). "For example, development of deafness, kidney malfunction and/or cataract in patients with MYH9-RD occur only in adult individuals and it has been reported that patients of the same MYH9-RD pedigrees have variable clinical manifestations." (PMID 31275945, 2019). "Here we report the clinical outcome of CI in 10 patients with MYH9-RD and severe to profound deafness." (PMID 24980457, 2014). "CI is safe and effective in most patients with MYH9-RD and severe to profound deafness and should be offered to these subjects, possibly as soon as they develop the criteria for candidacy." (PMID 24980457, 2014). "Almost all MYH9-RD patients develop the hearing defect, which, in many individuals, progresses to severe to profound deafness with high impact on quality of life." (PMID 24980457, 2014). "By international co-operative study, we report the clinical outcome of 10 patients with MYH9-RD and severe to profound deafness who received a CI at 8 institutions." (PMID 24980457, 2014). "This patient had a pathological phenotype compatible with MYH9-RD: macrothrombocytopenia and early deafness with onset at 10 years, and abnormal structure typical of MYH9-RD at EM." (PMID 25077172, 2014). "This study provides evidence that CI is safe and highly effective in restoring hearing ability in most patients with MYH9-RD and severe to profound deafness." (PMID 24980457, 2014). "Notably, in both D. melanogaster and vertebrate auditory structures, Zip/MYH9 and Ck/MYO7A genetically and physically interact, and mutations in both MYH9 and MYO7A are associated with deafness in humans." (PMID 40700419, 2025).
deafness (continued). "Deafness and MYH9-RDs: The patient’s grandmother had mild deafness, and there is a suspicion that it may be related to MYH9-RDs." (PMID 38134071, 2023). "Patients affected by MYH9-RD with severe to profound deafness are potential candidates for CI." (PMID 24980457, 2014). "Moreover, the effectiveness of CI in MYH9-related deafness was questioned in view of the discordant results obtained in two families with the non-syndromic deafness DFNA17." (PMID 24980457, 2014). "The efficacy of CI in MYH9-related deafness is made even more uncertain in view of the discordant results obtained in non-syndromic deafness DFNA17: members of both the reported DNFA17 pedigrees received CIs, with good outcomes in one family and very poor results in the other one." (PMID 24980457, 2014). "Cochlear implantation (CI) is a potential option for patients with MYH9-RD and severe to profound deafness, however, no consistent data are available about the risk to benefit ratio of CI in this condition." (PMID 24980457, 2014). "Further investigations into how MYH9 dysfunction results in deafness are required." (PMID 23976996, 2013). "It is therefore possible that the deafness that occurs in MYH9-related diseases might not be directly caused by hair cell defects." (PMID 29853544, 2018). "Thus, in many MYH9-RD patients deafness greatly contributes to patients’ disability." (PMID 24980457, 2014). "TECTA, WFS-1, MYH9, EYA1, COL4A5, COL11A1 were identified as the responsible genes for deafness in autosomal dominant families." (PMID 23967202, 2013). "TMPRSS3, MYO15A, GJB2, SLC26A4 were found to be responsible for deafness in autosomal recessive or sporadic families, while TECTA, WFS1, MYH9, EYA1, COL4A5 and COL11A1 were identified as the responsible genes for deafness in autosomal dominant families." (PMID 23967202, 2013). "Mutations in non-muscle myosins MYH9, MYH14 and myosin VIIa have been implicated in deafness in mammals." (PMID 21888654, 2011).
hepatocellular carcinoma (23 papers, 2020 to 2025). A malignant tumor that arises from hepatocytes. "For instance, resistance in hepatocellular carcinoma involves the p-MYH9/USP22 axis stabilizing HIF-1alpha, promoting stemness and lenvatinib resistance, while in pancreatic cancer, targeting MXD1 overcomes trametinib resistance." (PMID 40696490, 2025). "Hepatocellular carcinoma upregulated long non-coding RNA (HULC) is an oncogenic long non-coding RNA (lncRNA) that acts like a molecular sponge for miR-9-5p mRNA to regulate MYH9 expression." (PMID 39273383, 2024). "NAP1L5 inhibits tumor growth and metastasis by inhibiting the PI3K/Akt/mTOR signaling pathway and myosin heavy chain 9 in hepatocellular carcinoma." (PMID 37667226, 2023). "High expression of MYH9 conferred a poor prognosis for hepatocellular carcinoma, which was consistent with our results." (PMID 36612298, 2023). "MYH9 plays oncogenic roles in hepatocellular carcinoma by enhancing cancer stemness properties, metastasis, and proliferation." (PMID 36345155, 2023). "A further study showed that MYH9 overexpression leads to epithelial-to-mesenchymal transition and stemness in hepatocellular cancer." (PMID 37770914, 2023). "In the mechanistic study, we found that NAP1L5 affects the occurrence and development of hepatocellular carcinoma by regulating MYH9 to inhibit the PI3K/AKT/mTOR signaling pathway." (PMID 36374212, 2022). "C-Jun transcriptionally stimulated MYH9 expression to form MYH9/GSK3B/β-catenin/JUN feedback loop regulating CSC properties in hepatocellular carcinoma." (PMID 35242279, 2022). "We proved the interaction between NAP1L5 and MYH9 by mass spectrometry and Co-IP and found that they regulated the downstream signaling pathways and functions of hepatocellular carcinoma cells." (PMID 36374212, 2022). "Many previous studies have confirmed that MYH9 promotes the occurrence and development of hepatocellular carcinoma, such as the research of Professor Fang Weiyi of Southern Medical University on the role of MYH9 in HCC." (PMID 36374212, 2022). "The promotive role of MYH9 in hepatocellular carcinoma was confirmed, in accordance with previous studies." (PMID 36374212, 2022). "Up to now, many studies have shown that MYH9 is an oncogene in human cancer, including hepatocellular carcinoma, ovarian cancer, pancreatic cancer and OS." (PMID 33356805, 2021). "Here, we found that MYH9 is an effective promoter of tumor stemness that facilitates hepatocellular carcinoma pathogenesis." (PMID 32296025, 2020). "In clinical samples, high MYH9 expression levels predicted poor prognosis of hepatocellular carcinoma patients." (PMID 32296025, 2020). "Based on TCGA database analysis, MYH9 was found to be elevated and conferred poor prognosis for hepatocellular carcinoma patients." (PMID 32296025, 2020). "Therefore, we believe that MYH9 can act as the downstream molecule of TM4SF1 in hepatocellular carcinoma cells and be subject to unilateral positive regulation from TM4SF1." (PMID 37069693, 2023). "NAP1L5 inhibits the PI3K/AKT/mTOR signaling pathway in hepatocellular carcinoma by regulating MYH9." (PMID 36374212, 2022). "Likewise, another study on hepatocellular carcinoma has revealed that an MYH9/GSK3β/β-catenin/c-Jun regulatory circuit improves cancer stemness, migration, invasion, and resistance to sorafenib." (PMID 34425650, 2021). "Importantly, targeting MYH9 remarkably improved the survival of hepatocellular carcinoma-bearing mice and promoted sorafenib sensitivity of hepatocellular carcinoma cells in vivo." (PMID 32296025, 2020). "MYH9 can also interact with GSK3β and facilitate GSK3β ubiquitination and degradation to favor cancer stemness properties in hepatocellular carcinoma, illustrating that KRT19/MYH9 may coordinate cell fate specification via orchestrating regulatory hubs with GSK3β." (PMID 41345704, 2025).
hepatocellular carcinoma (continued). "Increased expression of the MYH9 gene is frequently observed in respiratory neoplasms, including lung cancer, reproductive tumors such as ovarian cancer, prostate cancer, as well as digestive system tumors like hepatocellular carcinoma (HCC), colorectal cancer (CRC) and esophageal cancer (EC)." (PMID 39149512, 2024). "Over the past several years, an increasing number of studies have shown that MYH9 is upregulated in many cancers, such as non-small cell lung cancer, colorectal cancer, prostate cancer, diffuse large B-cell lymphoma, renal cell carcinoma, glioma, and hepatocellular carcinoma." (PMID 37770914, 2023). "Also, MYH9 could bind with and degrade GSK3β through ubiquitin, therefore β-catenin was downregulated to induce the epithelial-mesenchymal transition in hepatocellular carcinoma." (PMID 35369347, 2022). "Furthermore, in hepatocellular carcinoma (HCC), targeting Myh9 improved the survival of HCC-bearing mice markedly and promoted sorafenib sensitivity of HCC cells." (PMID 36911682, 2023). "Accordingly, the MYH9 circular product has recently been reported to play a similar role in cancer cells’ fate by increasing the mRNA stability of Karyopherin α2 (KPNA2), another known oncogene in hepatocellular carcinoma." (PMID 36900344, 2023). "Previous studies found the interaction between MYH9 and GSK3-β in hepatocellular carcinoma and nasopharyngeal carcinoma, and GSK3-β could induce the degradation of β-catenin." (PMID 34743203, 2022).
colorectal cancer (21 papers, 2020 to 2026). A primary or metastatic malignant neoplasm that affects the colon or rectum. "MYH9 was also highly expressed in most colorectal cancer patients, and was significantly associated with patient age, clinical stage, lymph node metastasis, and metastasis distance." (PMID 35646686, 2022). "MYH9, a cytoskeletal protein critical for cell motility and morphology, exhibits oncogenic properties in various malignancies including liver cancer, colorectal cancer, and prostate cancer." (PMID 40416600, 2025). "Another study reported MYH9 significantly enhanced MAPK/AKT pathway, and was remarkably associated with poor prognosis in colorectal cancer." (PMID 35318312, 2022). "It has been reported that MYH9 significantly increases tumorigenesis in colorectal cancer through the activation of MAPK/AKT signaling pathway, which mediates the epithelial mesenchymal transition and correlates with poor prognosis." (PMID 34425650, 2021). "The expression of MYH9 is upregulated in other cancers, such as colorectal cancer, head and neck cancer, and acute myeloid leukemia, and is associated with poor prognosis of these cancers." (PMID 34635641, 2021). "MYH9, a well-known cytoskeleton molecule, is closely related to the proliferation and metastasis of human colorectal cancer." (PMID 32413870, 2020). "MYH9, a well-known cytoskeleton molecule, is closely related to the proliferation and migration of colorectal cancer and participates in the EMT process." (PMID 32413870, 2020). "MiR-214-3p suppressed the malignant behaviors of colorectal cancer by regulating the PLAGL2/MYH9 axis." (PMID 32413870, 2020). "In glioma and colorectal cancer, MYH9 may induce PI3-Akt/Akt signaling to facilitate cancer growth and metastasis." (PMID 36139430, 2022). "MYH9 may promote cell growth in colorectal cancer, induce stem-like properties in lung cancer, and reduce chemosensitivity in gliomas and colorectal cancer." (PMID 36139430, 2022). "MYH9 may activate mTOR signaling in lung and colorectal cancers to induce cancer stem-like or chemo-resistant phenotypes." (PMID 36139430, 2022). "A recent study reported that MYH9 promotes CRC cell growth and metastasis via activation of MAPK/AKT signaling in colorectal cancer." (PMID 35646686, 2022). "Furthermore, MYH9 may be a biomarker for diagnosis and a target for the treatment of colorectal cancer.Whether 4H12 mAb has a blocking effect on MYH9 in acinar cell carcinoma cell or can inhibit its growth and metastasis needs further in vitro and in vivo studies." (PMID 34425650, 2021). "For instance, MYH9 facilitates the cell EMT and migration of colorectal cancer by activating MAPK/AKT signalling, and promotes cell invasion and radioresistance in head and neck cancer by modulating the cellular ROS levels via activation of the MAPK/Nrf2/GCLC axis." (PMID 37875476, 2023). "MAP7D2 interacts with the MYH9 protein to protect it from ubiquitin-mediated degradation, subsequently reducing the secretion of HMGB1 to inhibit the infiltration of CD8+ cytotoxic T lymphocytes in microsatellite-stable colorectal cancer." (PMID 37875476, 2023). "MYH9, which interacts significantly with ATG9B, facilitates colorectal cancer invasion through non-autophagic mechanisms." (PMID 39149512, 2024).
hearing loss (20 papers, 2012 to 2026). "Our data will be useful for providing more appropriate treatment and follow-up for MYH9-associated hearing loss." (PMID 41751538, 2026). "There is still no conditional mouse model study utilizing outer hair cell (OHC)–specific Cre, such as Prestin-CreERT2+/−, to investigate the role of MYH9 or MYH10 in hearing loss." (PMID 40464565, 2025). "The deletion in 22q in patient 13 was classified as being probably pathogenic since the patient had hearing impairment, and this region is associated with the MYH9, which is responsible for cochleosaccular degeneration (OMIM #603622)." (PMID 31568707, 2020). "Patients with MYH9/10/14 mutations are at risk of hearing loss." (PMID 40464565, 2025). "Finally, the non‐muscle myosin Type IIA (MYH9) has been linked to both syndromic and nonsyndromic hearing loss due to the disruption of the hair cell stereociliary bundles." (PMID 36594367, 2023). "It has been documented that several syndromic and non-syndromic types of hearing loss are caused by mutations of the myosin II genes, such as the p.R702H, p.R702C and p.R705H mutations in myosin heavy-chain 9 (MYH9) and the p.S7X, p.S120L, p.G376C and p.R726S mutations in MYH14." (PMID 22485190, 2012). "Myh9 mutants recapitulate similar disease phenotypes found in humans with MYH9-related diseases as all develop hematologic defects, and some develop kidney abnormalities, cataracts, and hearing loss, which have allowed for critical advances in the understanding of genotype-phenotype connections." (PMID 39503257, 2025). "Two genes encoding conventional myosins, MYH9 and MYH14, and four genes encoding unconventional myosins, MYO3A, MYO6, MYO7A and MYO15A, are associated with nonsyndromic hereditary hearing loss in human." (PMID 38562617, 2024). "Myosin genes are known to be responsible for 10 types of syndromic as well as non‐syndromic hearing loss (MYO7A, DFNA11/DFNB2/USH1B; MYH9, DFNA17; MYH14, DFNA4; MYO6, DFNA22/DFNB37, MYO3A, DFNB30; MYO15A, DFNB3)." (PMID 32027099, 2020). "Thus, the molecular mechanism by which MYH9 mutations cause hearing loss remains unclear." (PMID 29853544, 2018). "Some of the tissue specific proteins were found to be involved in pathophysiology of rare, genetic, or syndromic diseases associated with hearing loss, e.g., Collagen type 2 alpha 1 chain (COL2A1) in Stickler syndrome 1 or Myosin heavy chain 9 (MYH9) in various syndromes." (PMID 35573665, 2022). "However, two patients who respectively carried KCNQ c.546C>G and MYH9 c.2114G>A presented prelingual and profound hearing impairment." (PMID 27018795, 2016). "While MYH9 mutations are linked to hearing loss in humans with no significant immune implications, uncharacterized ubiquitination of other proteins may play a role in T-cell modulation." (PMID 41023441, 2025).
cataract (19 papers, 2013 to 2025). Partial or complete opacity of the crystalline lens of one or both eyes that decreases visual acuity and eventually results in blindness. "Mutations in the human MYH9 gene can cause cataracts and are also associated with various tissue pathologies, including thrombocytopenia, platelet macrocytosis, proteinuric neuropathy, and sensorineural deafness." (PMID 37070941, 2023). "MYH9 disorders frequently cause nephritis, sensorineural hearing disability and cataracts." (PMID 23976996, 2013). "Between 16% and 18% of MYH9-RD patients present with presenile cataracts with a mean onset age of 23 to 37 years old." (PMID 37070941, 2023). "Early-onset cataracts are the rarest feature of MYH9-RD patients." (PMID 32545517, 2020).